RAB27B (RAB27B, member RAS oncogene family)
Diseases named in the same sentence as RAB27B in open-access papers (continued):
Sharing a sentence is not in itself a finding about the gene and the disease.
colorectal cancer (15 papers, 2014 to 2025). A primary or metastatic malignant neoplasm that affects the colon or rectum. "GOLT1A has been reported to be differentially expressed between high and low risk groups for esophageal cancer and RAB27B is a significant prognostic marker for metastasis and poor prognosis in colorectal cancer." (PMID 38632500, 2024). "Increased expression of RAB27B is associated with malignant progression of ovarian cancer, glioblastomas, colorectal cancer and HCC." (PMID 28977851, 2017). "However, the association between Rab27b expression and the clinical characteristics of colorectal cancer (CRC) is barely investigated." (PMID 25580113, 2014). "High RAB27B expression is shown to be an unfavorable prognostic factor in many solid cancers such as non-small cell lung carcinoma, colorectal cancer, and ovarian cancer; however, its role in leukemia was poorly established." (PMID 37317963, 2023). "The activated RAB27B expression will promote the secretion of colorectal cancer stem cell exosomes." (PMID 33665205, 2020). "In colorectal cancer stem cells, Rab27b has a unique role in controlling the exosomal pathway in colorectal cancer stem cells for TME regulation, and it has been demonstrated that targeting Rab27b is beneficial for anti-tumor therapy." (PMID 39524543, 2025). "Elevated RAB27A has been identified as a positive prognostic marker of colorectal cancer, whereas a decrease of both RAB27A and RAB27B expression correlates with increased metastasis and poor outcome." (PMID 35091681, 2022).
bladder cancer (10 papers, 2018 to 2025). "Elevated levels of Rab27B were found to be associated with poor prognosis in two independent cohorts of patients with bladder cancer corresponding to 196 and 294 tumors." (PMID 30081925, 2018). "Furthermore, it was suggested that disposal of tumor-suppressive miRNA via exosome release through the function of RAB27B is associated with acquisition of metastatic properties in bladder cancer." (PMID 32379831, 2020). "In bladder cancer cells, AR activity was positively and inversely correlated with the expression of Rab27b and the amount of intracellular BCG, respectively." (PMID 40486871, 2025). "Mechanistically, LINC00665 induces lymphatic metastasis via RAB27B-HGF-c-Myc loop between bladder cancer cells and CAFs." (PMID 39726782, 2024). "The cancer-promoting role of Rab27 was confirmed in vitro; knockdown of Rab27A or Rab27B suppressed cell invasion in bladder cancer cells." (PMID 30081925, 2018). "In a study of bladder cancer, knockdown of Rab27A or Rab27B attenuated cell invasion, reduced exosome release, and increased intracellular levels of miR-23b and miR-921." (PMID 30081925, 2018). "Knockdown of Rab27B by siRNA suppresses in vitro cell invasion of bladder cancer cells (T24, FL3)." (PMID 30081925, 2018). "In bladder cancer, the long non-coding RNA LINC00665 within TDEVs epigenetically upregulates RAB27B expression, forming a RAB27B-HGF-c-Met positive feedback loop that enhances lymphangiogenesis and lymph node metastasis." (PMID 41459253, 2025). "Subsequent research revealed that LINC00665 enhances RAB27B expression, thereby inducing a RAB27B-HGF-c-Myc positive feedback loop that promotes lymphangiogenesis and lymph node metastasis in bladder cancer." (PMID 39628486, 2024). "Knockdown of Rab27A or Rab27B reduces exosome release in T24 and FL3 bladder cancer cells and HeLa cervical cancer cells." (PMID 30081925, 2018). "Furthermore, RAB27B-mediated EV secretion activates fibroblasts to CAF phenotype, which reciprocally induces LINC00665 overexpression to form a RAB27B-HGF-c-Myc positive feedback loop, promoting lymphangiogenesis and lymphatic metastasis of bladder cancer." (PMID 39726782, 2024).
lymph node metastasis (8 papers, 2010 to 2023). "Another study identified that RAB27B expression correlated to lymph node metastasis and poor prognosis in patients with LUAD." (PMID 37077938, 2023). "High Rab27b cytoplasm expression was significantly correlated with lymph node metastasis (p = 0.016) and TNM stage (p = 0.019)." (PMID 30627227, 2018). "In survival analysis, Rab27b expression, lymph node metastasis, N status, and TNM stage were screened as four elements that were significantly associated with the overall survival of LUAD patients by using a univariate mode." (PMID 30627227, 2018). "Rab27b expression was statistically correlated with lymph node metastasis (p = 0.016) and TNM stage (p = 0.019)." (PMID 30627227, 2018). "The univariate analysis firstly screened four factors that were associated with the overall survival of 80 LUAD cases, including Rab27b expression (p = 0.002), lymph node metastasis (p = 0.007), N status (p = 0.014), and TNM stage (p = 0.001)." (PMID 30627227, 2018). "High expression of Rab27B was positively correlated with pathology grade, advanced clinical stage, lymph node metastasis, and ER status (P < 0.05)." (PMID 23217148, 2012). "In this study, we found that those with higher Rab27B expression are prone to have lymph node metastasis." (PMID 23217148, 2012). "The elevated expression of Rab27B was closely correlated with lymph node metastasis, advanced clinical stage, ascending pathology classification, and positive ER status." (PMID 23217148, 2012). "In this study, we found that those CRC patients with higher Rab27b expression are prone to have lymph node metastasis and distant metastasis and hence we hypothesize that Rab27b may be identified as a new predictor of metastasis status in CRC." (PMID 25580113, 2014). "Furthermore, the accuracy of predicting lymph node metastasis by examining Rab27B expression level (high vs. low) in our cohort is 60.7% (65/107)." (PMID 23217148, 2012). "Moreover, in a study of two independent cohorts of patients with estrogen receptor-positive breast cancer, high expression of Rab27B was shown to be correlated with lymph-node metastasis and pathological grade, suggesting a role of Rab27B in promoting cancer metastasis." (PMID 30081925, 2018). "High Rab27b protein expression was significantly related to serum CEA level (P = 0.004), lymph node metastasis (P = 0.001), distant metastasis (P = 0.009), and TNM stage (P = 0.001)." (PMID 25580113, 2014).
acute myeloid leukemia (6 papers, 2020 to 2025). Acute myeloid leukemia (AML) is a group of neoplasms arising from precursor cells committed to the myeloid cell-line differentiation. "RAB27B overexpression in myeloid malignancies with CBL or JAK2 mutations correlates with poor acute myeloid leukemia (AML) prognosis." (PMID 40977744, 2025). "Our proteomic studies revealed RAB27B upregulation in CBL- or JAK2-mutated myeloid malignancies, and its expression correlated with poor prognosis in acute myeloid leukemias (AMLs)." (PMID 37317963, 2023). "We made an attempt to study the impacts of RAB27B on the proliferation and apoptosis of acute myeloid leukemia (AML) cells." (PMID 35164665, 2022). "Increased expression of RAB27B in acute myeloid leukemia is positively correlated with patients’ poor prognosis." (PMID 35164665, 2022). "Similarly, RAB27B is upregulated in CD34+ acute myeloid leukemia (AML) CSCs and to plays a role in the stemness of these cells." (PMID 38765006, 2024). "A recent study realized by Peng and coworkers showed that the specific targeting of Rab27B in order to interfere with exosomes secretion could eliminate acute myeloid leukemia (AML) stem cells." (PMID 34072080, 2021). "Rab27b facilitates exosome shedding in acute myeloid leukemia (AML) KG-1a cells." (PMID 32322256, 2020).
pancreatic cancer (6 papers, 2016 to 2025). "RAB27B (a member of RAS oncogene family) expression is associated with perineural invasion and higher metastatic potential of pancreatic cancer cells and it plays a crucial role in altered exosome shedding and selective loading of exosomal cargo." (PMID 40680814, 2025). "Further, in pancreatic cancer, EVs released by upregulated RAB27B activated p38 MAPK." (PMID 32379831, 2020). "Furthermore, five genes (KRT19, ALDOA, CLDN4, RAB27B, and GJB5) among the top 10 % coregulated genes were identified to have significantly elevated expression in pancreatic cancer compared to the normal pancreas." (PMID 40680814, 2025).
glioma (5 papers, 2018 to 2022). A benign or malignant brain and spinal cord tumor that arises from glial cells (astrocytes, oligodendrocytes, ependymal cells). "Although hypomethylated RAB27B is reported to be a progression-associated prognostic biomarker in glioma, the regulatory mechanisms of RAB27B expression remain to be defined." (PMID 32379831, 2020). "We further investigated paracrine effects mediated by Rab27b after X-ray irradiation using coculture systems of glioma cell lines." (PMID 33409495, 2020). "To further evaluate the expression of EREG and Rab27b in glioma cell lines, we analyzed the protein levels in the H4 (neuroglioma), SW1088 (astrocytoma), A172 (GBM), U118MG (GBM), and U87MG (GBM) cells." (PMID 33409495, 2020). "Interestingly, the co-upregulation of Rab27b and epiregulin (EREG), a member of the epidermal growth factor (EGF) family, correlated with radioresistance in glioma cell lines." (PMID 33409495, 2020). "Furthermore, Rab27b regulates the expression of EREG and further participates in paracrine signaling by activating EGF receptor (EGFR) in different types of glioma cells after IR treatment." (PMID 33409495, 2020).
leukemia (5 papers, 2021 to 2025). A malignant (clonal) hematologic disorder, involving hematopoietic stem cells and characterized by the presence of primitive or atypical myeloid or lymphoid cells in the bone marrow and the blood. "RAB27B depletion impaired the PM localization of NRAS in both NRAS-mutated leukemia and melanoma cells." (PMID 37317963, 2023). "Interestingly, a recent study indicated that the loss of RAB27B inhibited EV release and altered the protein composition of EVs from leukaemia stem cells." (PMID 39723610, 2024). "Notably, RAB27B was important for the growth of leukemia cells with CBL or NRAS mutations." (PMID 37317963, 2023). "By regulating NRAS palmitoylation, RAB27B facilitates ERK signaling activation to promote leukemia development." (PMID 39877903, 2025). "The enlarged size of MVBs was also observed upon RAB27B depletion in leukaemia stem cells, with unchanged subcellular localization." (PMID 39723610, 2024). "To study the mechanisms by which depletion of RAB27B inhibits leukemia cell growth, we evaluated intracellular signaling pathways important for the growth of hematopoietic cells, i.e., JAK-STAT, PI3K-AKT, and ERK." (PMID 37317963, 2023). "To further study the correlation between JAK2 signaling and RAB27B expression, we compared multiple leukemia cell lines and found that they exhibit a wide range of RAB27B and RAB27A expression levels." (PMID 37317963, 2023). "We revealed that GAS6-AS1 directly binds Y-box binding protein 1 (YBX1) to facilitate its interaction with MYC, leading to MYC transactivation and upregulation of IL1R1, RAB27B and other MYC target genes associated with leukemia progression." (PMID 34753494, 2021). "GAS6-AS1 promote the cooperation of YBX1 with MYC, leading to upregulation of downstream target genes associated leukemia progression, including IL1R1, SRC and RAB27B." (PMID 34753494, 2021). "Nonetheless, our data are consistent with the notion that RAB27B plays a critical role in leukemia cell growth when NRAS is required — such as in AMLs with oncogenic NRAS or CBL mutations — while it is dispensable for the growth of AMLs with other dominant mutations or in normal HSPCs." (PMID 37317963, 2023). "Notably, RAB27B is important for the growth of leukemia cells with CBL or NRAS mutations but does not affect normal hematopoiesis." (PMID 37317963, 2023). "In leukemia cells, RAB27B, a RAB family small GTPase, promotes the palmitoylation of NRAS, and the effect of RAB27B on NRAS palmitoylation relies on ZDHHC9, which interacts with RAB27B." (PMID 39877903, 2025). "We showed in this study that RAB27B depletion dramatically reduced NRAS palmitoylation, activity, and downstream RAF/MEK/ERK signaling in both leukemia cell lines and primary human AMLs." (PMID 37317963, 2023). "By regulating palmitoylation, RAB27B controlled c-RAF/MEK/ERK signaling and affected leukemia development." (PMID 37317963, 2023). "Thus, our results revealed what we believe to be a previously unappreciated role for RAB27B in regulating NRAS activity, signaling, and leukemia cell growth." (PMID 37317963, 2023). "RAB27B regulates NRAS activity, signaling, and leukemia cell growth." (PMID 37317963, 2023). "We found that RAB27B, but not RAB27A, expression was higher in leukemia cells compared with normal cells." (PMID 37317963, 2023).
melanoma (5 papers, 2018 to 2024). A malignant, usually aggressive tumor composed of atypical, neoplastic melanocytes. "We found that miR-195-5p overexpression in BRAF-mutated melanoma cells causes an increase in the expression levels of some EVs biogenesis-related genes like RAB27b, RAB31, and/or FLOT2, which was accompanied by a consequent increase in CD63 and CD9 positive EVs secretion." (PMID 37174717, 2023). "Our studies included three human melanoma cell lines, with various Rab27A and Rab27B expression levels, as well as their proliferative/invasive potential." (PMID 39596498, 2024). "Knockdown of Rab27A or Rab27B reduced tumor growth and metastasis in murine models of melanoma." (PMID 39596498, 2024). "Furthermore, double RAB27A and RAB27B KO in the A375 cell line did not lead to the inhibition of the number of sEVs released into the culture medium; thus, Rab27B did not compensate for the loss of Rab27A in these melanoma cells, even though Rab27B expression was enhanced significantly in RAB27A KO." (PMID 39596498, 2024). "The potential engagement of Rab27A and Rab27B in the loading of characteristic protein markers in the sEVs of melanoma cells is not related to their basal expression but is strictly dependent on the particular cell line." (PMID 39596498, 2024).
ovarian carcinoma (5 papers, 2017 to 2023). A malignant neoplasm originating from the surface ovarian epithelium. "Previous studies have found that increased expression of RAB27B is related to malignant progression of cancers, including breast, HCC, ovarian cancer, and glioblastomas." (PMID 28977851, 2017).
glioblastoma (4 papers, 2017 to 2022). The most malignant astrocytic tumor (WHO grade IV). "When assessing the expression of RAB27B, RAB11 and RAB35, which may be the main potential actors of such a compensation, the only protein exhibiting an enhancement was RAB27B in the glioblastoma model." (PMID 35216426, 2022). "The Rab27b protein level was specifically induced in irradiated human U87MG glioblastoma cells." (PMID 34884633, 2021). "The Rab27b-EREG pathway may improve the efficacy of radiotherapy for glioblastoma multiforme (GBM)." (PMID 34884633, 2021).
nasopharyngeal carcinoma (4 papers, 2017 to 2020). A carcinoma arising from the nasopharyngeal epithelium. "In nasopharyngeal cancer, the overexpression of miR‐20a stimulated radio‐resistance by targeting Rab27B to regulate cell apoptosis and radiosensitivity." (PMID 29266846, 2018). "MiR-20a-5p reduces the sensitivity of nasopharyngeal carcinoma cells to radiotherapy by targeting NPAS2 and Rab27B, and miR-193a-3p enhances the anti-radiation ability of NPC by targeting SRSF2 43-45." (PMID 32328201, 2020).
Alzheimer disease (3 papers, 2020 to 2023). A progressive, neurodegenerative disease characterized by loss of function and death of nerve cells in several areas of the brain leading to loss of cognitive function such as memory and language. "Interestingly, pathway analysis also showed an association between RAB27B and neurological diseases such as Huntington's disease, Parkinson's disease and Alzheimer's disease (AD)." (PMID 32379831, 2020). "The list included several known disease genes, such as INPP5D (Alzheimer’s disease), RAB27B (major depressive disorder, MDD), SORL1 (Alzheimer’s disease) and ZNF184 (MDD and schizophrenia)." (PMID 34446921, 2021).
lung adenocarcinoma (3 papers, 2018 to 2023). A carcinoma that arises from the lung and is characterized by the presence of malignant glandular epithelial cells. "However, the relationship between Rab27b expression and the clinical characteristics of lung adenocarcinoma (LUAD) is rarely explored." (PMID 30627227, 2018). "Kaplan–Meier Plotter analysis showed that lung adenocarcinoma patients with positive ATCR2, FHL1, RAB27B, and RAP1B expression had observably longer overall survival than patients with negative expression (P < 0.05)." (PMID 36404333, 2022). "In this research, samples of lung adenocarcinoma were interrogated with TME-related genes, among which high expression of PLK1, LDHA, FURIN, FSCN1, and RAB27B was correlated with poor OS, while high expression of MS4A1 was correlated with longer OS compared with the MS4A1 low expression." (PMID 37604869, 2023).
lung carcinoma (3 papers, 2021 to 2023). "It has been reported that the expression of rab27b, which is the main component of vesicles in exosomes, is significantly correlated with histological types of lung cancer patients, and lung cancer patients with high rab27b expression have a poor prognosis." (PMID 34500436, 2021). "For the reason that Rab27b, which is widely reported to participate in the secretion pathway of exosomes, is significantly upregulated in lung cancer cells, we analyzed the influences of Rab27b on the expression of miR-122 in A549 EVs." (PMID 34884671, 2021). "Quantitative PCR results showed that hnRNPA2B1 and Rab27b were significantly upregulated in A549 lung cancer cells." (PMID 34884671, 2021). "Because miR-122 is downregulated in lung cancer cells and upregulated in EVs derived from lung cancer, we selected hnRNPA2B1 and Rab27b, which were upregulated in lung cancer cells, as the potential research object." (PMID 34884671, 2021). "The results showed PLK1, LDHA, FURIN, FSCN1, and RAB27B were up-regulated in lung cancer tissues, and MS4A1 was down-regulated in lung cancer tissues." (PMID 37604869, 2023). "Furthermore, we also found that PLK1, LDHA, FURIN, FSCN1, and RAB27B were increased in NSCLC cancerous cell lines compared with that in normal human bronchial epithelium cell line BEAS-2B, MS4A1 was down-regulated in lung cancer cells lines." (PMID 37604869, 2023).
renal carcinoma (3 papers, 2020 to 2023). A carcinoma arising from the epithelium of the renal parenchyma or the renal pelvis. "Downregulated KEGG pathways in renal cancer cells transfected with si-RAB27B." (PMID 32379831, 2020). "Downregulated genes in renal cancer cells transfected with si-RAB27B." (PMID 32379831, 2020).
choroideremia (2 papers, 2013 to 2024). Choroideremia (CHM) is an X-linked chorioretinal dystrophy characterized by progressive degeneration of the choroid, retinal pigment epithelium (RPE) and retina. "They found that Rab38, Rab27a, Rab27b, and Rab42 are prenylated the slowest and concluded that this finding may implicate them in choroideremia, since they may be more impacted by REP-1 deficiency when only REP-2 is present." (PMID 38920696, 2024). "Our work points to possible contribution of Rab38 to the emergence of choroideremia in addition to Rab27a and Rab27b." (PMID 24358126, 2013).